LRRK2 (leucine rich repeat kinase 2)
Diseases named in the same sentence as LRRK2 in open-access papers (continued):
Sharing a sentence is not in itself a finding about the gene and the disease.
synucleinopathy (48 papers, 2011 to 2025). A neurodegenerative disease that is characterized by the abnormal accumulation of aggregates of alpha-synuclein protein in neurons, nerve fibers or glial cells. "The involvement of certain genes like leucine-rich repeat kinase 2 (LRRK2) and parkin, which are pathogenic for PD, has also been investigated in other synucleinopathies, like MSA." (PMID 39456145, 2024). "Other approaches focus on targeting various genes or proteins associated with alpha-synucleinopathies, such as glucocerebrosidase, LRRK2, and poly(ADP-ribose) polymerase-1 (PARP-1), or directly target α-syn aggregation using small molecules like Anle138b." (PMID 39666171, 2024). "Approximately 24% of LBs in idiopathic patients were LRRK2-positive, whereas in confirmed LRRK2-PD patients with G2019S mutation, the proportion of LRRK2-reactive LBs increased to 50%, implicating a pathogenic role of LRRK2 in synucleinopathies." (PMID 35152914, 2022). "Intriguingly, in models of synucleinopathy, LRRK2 inhibition can restore neuronal loss and motor deficits but worsens α-Syn clearance." (PMID 36233046, 2022). "In a model of synucleinopathy, LRRK2 caused inflammation by promoting a calcineurin-dependent pathway through the phosphorylation of Nuclear Factor of Activated T Cells 2 (NFATc2)." (PMID 36233046, 2022). "Autonomic dysfunctions are associated with genetic forms of synucleinopathies like LRRK2-associated PD." (PMID 34439578, 2021). "Mitochondrial dysfunction is prevalent in synucleinopathies as evidenced by clinical findings in patients with PD/DLB who carry genetic mutations of genes LRRK2 and PINK1 which are associated with mitochondrial function." (PMID 28283027, 2017). "A pre-symptomatic marker of α-synucleinopathy that predicts disease would be of particular relevance to pre-symptomatic treatment in LRRK2 mutation carriers since penetrance is incomplete with estimates of penetrance of the most common LRRK2 p.G2019S mutation ranging from 25% to 42.5%." (PMID 35813946, 2022). "However, both LRRK2 variants accelerated the progression of a tetO-aSN transgene-mediated neuronal loss and α-synucleinopathy in CaMKII-tTA/tetO-LRRK2/tetO-aSN transgenic mice and exacerbated the accompanying astrocytosis and microgliosis." (PMID 22615783, 2012). "Notably, we cannot exclude a pathogenic role of tau in humans with PD or other synucleinopathies or that tau reduction might be of benefit in specific forms of PD, for example, those caused by LRRK2 mutations." (PMID 22206005, 2011). "For the first time, we provide evidence that LRRK2-mediated hyperphosphorylated Rab proteins represent shared pathological features across synucleinopathies and tauopathies." (PMID 40661559, 2025). "In summary, we found increased Rab12 phosphorylation and localization of pS106-Rab12 to tau and α-synuclein pathology in tauopathies and synucleinopathies, including LRRK2 PD, iPD, DLB, AD and primary tauopathies." (PMID 40661559, 2025). "Patients carrying LRRK2, CHCHD2, and GBA mutations, as well as those with iPD, displayed similar co-neuropathologies, including positivity for p-α-syn, α-syn, ASyO5, 5G4 (synucleinopathy), and HT7 and AT8 (p-tauopathy)." (PMID 38751879, 2024). "Given the inconsistencies produced by the double mutant approach, fusion models of synucleinopathy were implemented in LRRK2 rodents." (PMID 37601008, 2023). "Long-term LRRK2 inhibition based on an appropriate dosing regimen can be efficacious and safe in attenuating synucleinopathy in PD." (PMID 36088364, 2022). "The progressive increase in striatal and cortical αSyn oligomers with age in our LRRK2 mutant mice provides a reliable biomarker to monitor synucleinopathy in the brain." (PMID 36088364, 2022). "Inhibition of mutant LRRK2 hyper-kinase activity to normal physiological levels offers an encouraging and safe disease-modifying therapy to improve the course of synucleinopathies." (PMID 36551997, 2022).
synucleinopathy (continued). "Nevertheless, our findings demonstrate the therapeutic potential of LRRK2 inhibitors to ameliorate synucleinopathy by reducing αSyn oligomer accumulation in ageing brains, a hitherto unreported fact." (PMID 36088364, 2022). "Long-term inhibition of mutant LRRK2 hyper-kinase activity to physiological levels presents an efficacious and safe disease-modifying therapy to ameliorate synucleinopathy in PD." (PMID 36088364, 2022). "In conclusion, this is a rare autopsy report of a patient with PD harboring LRRK2 G2385R variant, showing elevated phosphorylation of Rab10, a substrate of LRRK2, and characteristic pathology as synucleinopathy." (PMID 35931783, 2022). "LRRK2 KI models have been widely used to study the potential interaction between LRRK2 and α-synuclein in the development of synucleinopathy in PD." (PMID 35152914, 2022). "In this scenario, the Rab GTPases have been proposed as possible mediators, because they represent one of the main endogenous LRRK2 substrates and were found to be involved in LRRK2-dependent α-synucleinopathy propagation." (PMID 32848606, 2020). "Overexpression of LRRK2 has been shown to exacerbate while deletion of the Lrrk2 gene suppressed synucleinopathy lesions and α-synuclein-induced neurodegeneration in rodent models of synucleinopathy." (PMID 30150626, 2018). "Although mutations in genes such as LRRK2, PINK1 and DJ-1 have often been implicated in the pathophysiology of synucleinopathies, GBA1 mutations are the ones showing the highest prevalence." (PMID 28835999, 2018). "Administration of a selective LRRK2 kinase inhibitor slowed the propagation of α-synuclein in culture and reduced synucleinopathy lesions in a transgenic mouse model." (PMID 30150626, 2018). "Evidence has accumulated to suggest that LRRK2 plays a crucial role in the pathology of both familial and sporadic α-synucleinopathies." (PMID 23577227, 2013). "Clinically, LRRK2(G2019S) carriers with PD and idiopathic PD patients have a very similar disease with brainstem and cortical Lewy pathology (α-synucleinopathy) as histopathological hallmarks." (PMID 22615783, 2012). "In a series of 110 cases, including 66 synucleinopathies, 29 tauopathies and 3 non-specific nigral degeneration, the prevalence of positivity of pathogenic variants in LRRK2 gene was 1.8%." (PMID 40114783, 2025). "LRRK2 monoallelic or biallelic pathogenic variants usually predispose to synucleinopathy, although cases of neurodegeneration without synucleinopathy exist." (PMID 38916622, 2024). "Notably, some genetic traits associated with increased PD risk, such as LRRK2 and PRKN pathogenic variants, are associated with lower likelihood of both olfactory loss and underlying alpha-synucleinopathy." (PMID 39434044, 2024). "Beyond known PD genes GBA1 and LRRK2, rare variants AD genes (CD33, CR1 and PSEN2) and Aβ toxicity modifiers involved in RhoA/actin cytoskeleton regulation (ARGHEF1, ARHGEF28, MICAL3, PASK, PKN2, PSEN2) were shared risk factors across synucleinopathies." (PMID 38496508, 2024). "Interestingly, elevated GLA activity in the blood was reported in LRRK2-PD patients and patients with one of the forms of synucleinopathies (multiple system atrophy)." (PMID 36901867, 2023). "Several reports and this study suggest that LRRK2 inhibition may play a role in the protection of α-synucleinopathy." (PMID 35269482, 2022). "Administration of a LRRK2 kinase inhibitor into α-synuclein transgenic mice also significantly decreases the α-synuclein accumulation in several regions of the brain, including neocortex and striatum, further confirming the role of LRRK2 hyperactivity in synucleinopathy." (PMID 35152914, 2022). "Although a skin biopsy study reports that synucleinopathy is associated with LRRK2 G2385R28, no brain autopsy of PD with LRRK2 G2385R has been reported." (PMID 35931783, 2022).
synucleinopathy (continued). "Therefore, LRRK2 KI mice represent a good in vivo model to observe different stages of synucleinopathy under the co-influence of LRRK2 and secondary factors such as aging and genetics." (PMID 35152914, 2022). "Using a well-established model of synucleinopathy, two additional studies showed that LRRK2 influences formation of aSyn aggregates both in vitro and in vivo, and that the G2019S mutation increases sensitivity towards pathology and accelerates the progression of aSyn inclusion formation." (PMID 32365906, 2020). "In this scenario, of particular interest is the possibility that LRRK2 could influence the inflammatory and microglial response to progressive α-synucleinopathy within the CNS." (PMID 32848606, 2020). "Mutant LRRK2 could influence the development of PD-related α-synucleinopathy at different time points, altering its phosphorylation, aggregation, propagation, or clearance." (PMID 32848606, 2020). "In fact, studies proving that dysregulation of autophagy is instrumental to the LRRK2-associated synucleinopathy in vivo are lacking." (PMID 31920513, 2019). "The role of aging in LRRK2-induced synucleinopathy will be discussed." (PMID 31920513, 2019). "Finally, in a mouse model of synucleinopathy, administration of an LRRK2 kinase inhibitor reduced α-synuclein aggregation via enhanced interaction of α-synuclein with the lysosomal degradation pathway." (PMID 30150626, 2018). "Furthermore, our findings suggest that LRRK2 kinase activity can be targeted for the purpose of reducing synucleinopathy lesions." (PMID 30150626, 2018). "We found that LRRK2 is activated in neurodegenerative diseases and associated with tau pathology, evidenced by elevated Rab12 phosphorylation in DLB subjects with high tau pathology and labeling of GVBs as well as mature tau and α-synuclein pathology in tauopathies and synucleinopathies." (PMID 40661559, 2025). "Future work will investigate mechanisms by which the LRRK2 pathway associates with and mediates protein aggregation and GVBs, which may uncover interventions targeting protein aggregation related to LRRK2 activity, both in LRRK2 PD and across tauopathies and synucleinopathies." (PMID 40661559, 2025). "We hypothesize that the high pT73-Rab10 signatures in some LRRK2-negative iPD cases may be due to extensive and progressive peripheral and central α-synucleinopathy, further modified by the PD-linked gut microbiome." (PMID 38862989, 2024). "In this study, identical mutation sites in CHCHD2 (T61I), LRRK2 (G2019S, R1441G), SNCA (E46K, A53T, duplication), and GBA (N370S, E326K, L444P, N409S/D409H) were identified in both skin biopsies and brain autopsies, with synucleinopathy detected in both cutaneous and cerebral samples." (PMID 38751879, 2024). "Whilst there are no clinical biomarkers in routine use in PD which correlate with disease progression, accumulation of αSyn oligomers in the brain appears to be a useful marker of synucleinopathy in our LRRK2 mutant mice, which may potentially correlate with progression in the human disease." (PMID 36088364, 2022). "In mouse models, LRRK2 mutations alone have produced mild-to-no signs of severe synucleinopathy." (PMID 35152914, 2022). "Here we have used a Drosophila model of α-synucleinopathy and experiments in iPS cells and mice to define excessive stabilization of F-actin with consequent disruption of mitochondrial dynamics and function as a key common pathway perturbed by both α-synuclein and Lrrk/LRRK2." (PMID 34030727, 2021). "If inhibiting LRRK2 kinase activity or reducing total LRRK2 levels are efficient at reducing α-synuclein pathology, this may be a viable therapeutic avenue for all patients with PD and even other synucleinopathies." (PMID 30808409, 2019). "Thus, it was predicted that, similarly to αS, LRRK2 might be involved in neuroinflammation in sporadic cases of PD and related α-synucleinopathies." (PMID 22550610, 2012).
synucleinopathy (continued). "Thus, PD and α-synucleinopathies are now genetically considered to be within the spectrum of inflammatory diseases in which LRRK2 and parkin might be involved." (PMID 22550610, 2012). "We recently demonstrated that leucine-rich repeat kinase 2 (LRRK2) and nuclear factor of activated T cells 1 (NFAT1) modulate the neurotoxic inflammation in synucleinopathies mediated by microglia." (PMID 41258081, 2025). "The skin biopsy synucleinopathies of the CHCHD2, RAB39B, LRRK2, and GBA groups were the same as the brain autopsy synucleinopathies." (PMID 38751879, 2024). "Α-syn RT-QuIC can identify iPD-, LRRK2-, and GBA-positive synucleinopathies with 100% sensitivity and 100% specificity in skin biopsies." (PMID 38751879, 2024). "However, only half of PD patients carrying LRRK2 variants were found to contain brainstem synucleinopathy in postmortem studies, suggesting that some LRRK2 variants may not be involved in central synucleinopathy." (PMID 35395825, 2022). "However, most other Tg or KI mouse lines expressing pathogenic LRRK2 mutants under different promoter systems do not exhibit synucleinopathy, which may be in part explained by the insufficient amount of seeds required for α-synuclein aggregation." (PMID 33266247, 2020). "However, we recently demonstrated that the kinase activity of LRRK2 induced activation and nucleus translocation of NFAT1 in the microglia of the synucleinopathy mouse model." (PMID 41258081, 2025). "Patients with SNCA, LRRK2, or GBA variants have peripheral synucleinopathy, while patients with PRKN variants do not." (PMID 35395825, 2022). "It is also not clear if the model of α-synucleinopathy used in our study induces LRRK2 hyperactivation as was observed with rotenone treatment." (PMID 30808409, 2019). "High levels of these LRRK2 variants left endogenous aSN and Tau levels unaltered and did not exacerbate or otherwise modify α-synucleinopathy in mice that co-expressed high levels of LRRK2 and aSN in brain neurons." (PMID 22615783, 2012). "In conclusion, most LRRK2 rodents will not develop a PD-like synucleinopathy during their life but present with behavioral signs and functional changes that are reminiscent of prodromal PD, suggesting they can model the early cellular pathogenic events set in motion by the LRRK2 mutation." (PMID 37601008, 2023). "Therefore, in many neurons high LRRK2 levels are well tolerated and not sufficient to drive or exacerbate neuronal α-synucleinopathy." (PMID 22615783, 2012). "In conclusion, our study of peripheral cutaneous synucleinopathy characteristics in patients with genetic PD yielded several key findings: (i) P-α-syn was deposited in the peripheral cutaneous nerves of PD patients with CHCHD2, LRRK2, or GBA mutations but not in those with RAB39B or PRKN mutations." (PMID 38751879, 2024). "Indeed, the coexpression of LRRK2 and α-syn genes was not followed by changes in the extent of the α-synucleinopathy or α-syn phosphorylation state, and the overexpression of human G2019S LRRK2 did not modify the α-synucleinopathy characterizing A53T α-syn transgenic mice." (PMID 32848606, 2020). "However, the mechanism by which LRRK2 exerts its action in synucleinopathy is not fully understood." (PMID 30150626, 2018). "Curiously, neither mitochondria nor LRRK2 was present in the swellings of mice expressing P123H β-synuclein, suggesting that α- and β-synuclein might play differential roles in the mitochondrial pathology of α-synucleinopathies." (PMID 23577227, 2013).
dementia (43 papers, 2013 to 2025). Loss of intellectual abilities interfering with an individual's social and occupational functions. "GBA1 PD carries more risk of dementia, whereas LRRK2 PD appears to have a more restricted pattern of neurodegeneration and reduced risk of dementia." (PMID 40926580, 2025). "We have also shown that variation at the 5′ end of the SNCA gene and variant tagging LRRK2 G2019S are associated with a significantly reduced risk of dementia." (PMID 38978726, 2024). "Genetic variants of the GBA and LRRK2 genes are known risk factors for the development of PD and dementia associated with accumulation of Lewy bodies." (PMID 36774388, 2023). "We observed that LRRK2 mutation was directly associated with a lower risk of dementia (β = −0.757, p = 0.029), and its association with dementia was partly mediated (β = −0.717, p < 0.05) by the estimated change of NfL." (PMID 37699957, 2023). "Our results confirm that in LBD, LRRK2 G2019S mutation status is associated with a decreased odds of progression towards dementia." (PMID 37987016, 2023). "We found that risk alleles rs429358 tagging APOEe4 and rs7668531 near the MMRN1 and SNCA-AS1 genes, increase the odds of developing dementia and that an intronic variant rs17442721 tagging LRRK2 G2019S, on chromosome 12 is protective against dementia." (PMID 37987016, 2023). "In a recent clinicopathological survey of 37 LRRK2 mutation carriers, progression to dementia was associated with elevated LB pathology." (PMID 31733655, 2019). "Of the 12 LRRK2 mutation carriers in our cohort, 11 presented clinically with PD, and 4 of those developed dementia over the disease course." (PMID 31733655, 2019). "LRRK2 mutation carriers in PD have a lower rate of dementia, perhaps providing further evidence against a role in DLB." (PMID 30097731, 2018). "In agreement with this, others have shown that GBA encoded PD is more prone to developing dementia than LRRK2-encoded disease." (PMID 24973356, 2014). "Notably, among the 4660 individuals with LRRK2 variants, 0.4% (n = 18) had an atypical parkinsonian disorder, and 1.0% (n = 48) had other diseases (such as immunological diseases, cancer, dementia, or essential tremor)." (PMID 39962078, 2025). "We have also shown that LRRK2 G2019S is associated with a dramatically reduced risk of dementia." (PMID 37987016, 2023). "However, baseline NfL did not have a significant mediation effect on the relationship between LRRK2 mutation and dementia." (PMID 37699957, 2023). "Whether APOE E4 carrier status poses a similar risk of dementia in LRRK2 and/or GBA1 PD is unknown." (PMID 40926580, 2025). "CSF levels of LRRK2 are also increased with age, and in a recent study, the highest levels of CSF LRRK2 were found in patients with dementia." (PMID 40437812, 2025). "Specifically, dementia is rare in PD with PRKN mutations, and less common in PD with LRRK2 mutations than in the idiopathic form." (PMID 40722695, 2025). "Other studies of monogenic LRRK2, involving p.G2019S and p.R1441C, reported a lower prevalence of dementia compared to non-carriers." (PMID 41253790, 2025). "We found that risk allele rs429358 tagging APOEe4 increases the odds of developing dementia, and that rs7668531 near the MMRN1 and SNCA-AS1 genes and an intronic variant rs17442721 tagging LRRK2 G2019S on chromosome 12 are protective against dementia." (PMID 38978726, 2024). "In this data set, the rate of dementia in LRRK2 G2019S carriers is 5% as compared with 39% in the total data set." (PMID 38978726, 2024). "In this dataset, the rate of dementia in LRRK2 G2019S carriers is 5% as compared to 39% in the total dataset." (PMID 37987016, 2023). "In our mediation model, LRRK2 mutation exerted an indirect effect on dementia through the longitudinal change of serum NfL, suggesting that NfL might play additional roles beyond being solely a biomarker of neural damage in the context of LRRK2-related dementia." (PMID 37699957, 2023).